SRA1 (steroid receptor RNA activator 1)
Diseases named in the same sentence as SRA1 in open-access papers (continued):
Sharing a sentence is not in itself a finding about the gene and the disease.
ovarian endometriosis (3 papers, 2020 to 2021). A non-neoplastic disorder characterized by the growth of endometrial tissue in the ovaries. "Knockdown of SRA1 in ovarian endometriosis increased estrogen receptor (ER)-alpha expression at the expense of ER-beta." (PMID 33879202, 2021). "Silencing of SRA1 via regulating ER expression could decrease stromal cells growth in ovarian endometriosis." (PMID 32850438, 2020). "Another lncRNA, steroid receptor RNA activator 1 (SRA1) lncRNA, has been reported to act in concert with SRA1 to regulate the expression of estrogen receptors by affecting alternative splicing, and thereby the growth of stromal cells in ovarian endometriosis." (PMID 34768856, 2021).
schizophrenia (3 papers, 2013 to 2024). A major psychotic disorder characterized by abnormalities in the perception or expression of reality. "The CYFIP1/SRA1 gene is located in a chromosomal region linked to various neurological disorders, including intellectual disability, autism, and schizophrenia." (PMID 24050404, 2013).
breast tumors (2 papers, 2009 to 2018). "SRA1 expression was higher in breast tumors compared with adjacent normal breast tissue." (PMID 30545127, 2018).
Hepatic steatosis (2 papers, 2021 to 2022). Steatosis is a term used to denote lipid accumulation within hepatocytes. "Furthermore, in these tissues/organs, SRA1 regulates several pathophysiological processes such as myocyte/adipocyte differentiation, hepatic steatosis, stem cell function, steroidogenesis, mammary gland development, and tumorigenesis." (PMID 36552771, 2022). "The role of SRA1 and its coactivators in the regulation of mammary gland development, myocyte, and adipocyte differentiation, steroidogenesis, tumorigenesis, hepatic steatosis, stem cell function, lipid metabolism, glucose homeostasis, and insulin sensitivity in adipocytes has been well documented." (PMID 34685582, 2021).
Autoimmunity (1 paper, 2020). The occurrence of an immune reaction against the organism's own cells or tissues. "For example, a recent study using linkage analysis demonstrated that by selecting individuals with familial autoimmunity and polyautoimmunity as EP, it was possible to identify the SRA1 gene (LOD score = 5.48)." (PMID 32854191, 2020).
Chronic Heart Failure (1 paper, 2024). "Thus, SRA1 is a potential molecular indicator formonitoring chronic heart failure development." (PMID 39076490, 2024).
heart failure (1 paper, 2024). Inability of the heart to pump blood at an adequate rate to meet tissue metabolic requirements. "Furthermore,SRA1 was found to alleviate the hypoxia-induced injury of cardiomyocytes,signifying its importance in treating hypoxia-induced heart failure." (PMID 39076490, 2024).
hypogonadism (1 paper, 2020). A disorder characterized by decreased function of the gonads. "The previously reported AR, probably pathogenic p.Ile179Thr variant in the SRA1 gene was identified in heterozygosity in patient 3, a 19-year-old male with partial hypogonadism and upper limb defects." (PMID 32982993, 2020).
hypogonadotropic hypogonadism (1 paper, 2016). Abnormal ovarian or testicular function due to insufficient hormonal stimulation from the hypothalamic-pituitary axis. "Therefore, inactivating SRA1 mutations in our patients in this study must have caused hypogonadotropic hypogonadism by a mechanism other than via a decreased ER-alfa coactivation either at the hypothalamic or the pituitary level." (PMID 27086651, 2016).
keloid (1 paper, 2026). An irregularly shaped, elevated mark on the skin caused by deposits of excessive amounts of collagen during wound healing. "Mendelian randomization identified 11 genes causally linked to keloid risk, with genetically determined downregulation of SSR1 and SRA1 associated with increased susceptibility." (PMID 41986576, 2026).
leiomyoma (1 paper, 2024). A well-circumscribed benign smooth muscle neoplasm characterized by the presence of spindle cells with cigar-shaped nuclei, interlacing fascicles, and a whorled pattern. "Additionally, the expression level of the lncRNA SRA1 has been observed to correlate with the MED12 mutation status in leiomyomas." (PMID 39519092, 2024).
myocardial infarction (1 paper, 2023). Gross necrosis of the myocardium, as a result of interruption of the blood supply to the area, as in coronary thrombosis. "The MED12-UL demonstrate changes in the expression of the SRA1 (steroid receptor RNA activator 1) and MIAT (myocardial infarction-associated transcript) lncRNAs, which regulate steroidogenesis and ECM accumulation, respectively." (PMID 36982825, 2023).
osteosarcoma (1 paper, 2024). A usually aggressive malignant bone-forming mesenchymal neoplasm, predominantly affecting adolescents and young adults. "An anti-cancer function of SRA1 was observed in osteosarcomas, in which SRA1 diminished the migratory, replicative, and invasive properties of the tumor cells and also acted as a sponge for miRNA-208a, thus promoting apoptosis." (PMID 39015175, 2024).
Parkinson disease (1 paper, 2020). A progressive degenerative disorder of the central nervous system characterized by loss of dopamine producing neurons in the substantia nigra and the presence of Lewy bodies in the substantia nigra and locus coeruleus. "The loci within these eQTL scores have been reported to regulate expression of genes involved in various brain-related processes and disorders, such as neurite outgrowth and Parkinson’s disease (DCAKD, SLC35A4, SEC14L4, SRA1, NMT1, CPNE1, PLEKHM1, UBE3C)." (PMID 32066731, 2020).
Primary amenorrhea (1 paper, 2020). "The known p.Ile179Thr variant in the SRA1 gene was also identified in the homozygous state in patient five, a 30-year-old female with CHH and primary amenorrhea." (PMID 32982993, 2020).
prostatic neoplasm (1 paper, 2018). "Several works also reported on the involvement of SRA1 and XIST in prostatic neoplasm." (PMID 29671405, 2018).
Uterine leiomyoma (1 paper, 2021). The presence of a leiomyoma of the uterus. "The present results suggest that SRA1 may explain the phenotypic difference observed in the tumor sizes of uterine leiomyoma samples considering the MED12 mutation pattern." (PMID 34122542, 2021). "Expression of SRA1 was higher in uterine leiomyoma samples without MED12 mutations than in uterine leiomyoma samples harboring MED12 mutations." (PMID 34122542, 2021).
tumor (13 papers, 2009 to 2025). "The Sra1 gene encodes the steroid receptor RNA activator protein and is involved in breast tumorigenesis and tumor progression." (PMID 37623890, 2023). "A striking observation in our study was the consistent upregulation of SRA1 expression in ESCC tumor tissues, with elevated SRA1 levels correlating with a poorer prognosis for patients." (PMID 38584841, 2024). "This heightened inflammatory state suggested that SRA1 may exert an anti-inflammatory effect, and its absence could promote inflammation within the tumor microenvironment." (PMID 38584841, 2024). "Interestingly, a consistent upregulation of SRA1 expression in tumor tissues compared to adjacent tissues was observed across different cohorts." (PMID 38584841, 2024). "By disrupting this fundamental metabolic pathway, SRA1 knockdown may deprive cancer cells of their primary energy source, thereby exerting cytotoxic effects and impeding tumor proliferation." (PMID 38584841, 2024). "Our analysis provided a significant increase in SRA1 expression within tumor as compared to adjacent noncancerous tissues." (PMID 38584841, 2024). "Among these samples, only four showed no detectable effective SRA1 expression, while 75% of the tumor samples exhibited an upregulation of SRA1 expression." (PMID 38584841, 2024). "Firstly, we selected several genes related to tumor metastasis through the NCBI database and literature, including SRA1, DBF4 zinc finger B (DBF4B), ZNFX1 antisense RNA 1 (ZFAS1), colorectal neoplasia differentially expressed (CRNDE), endoplasmic reticulum lectin (OS9), and others." (PMID 34011971, 2021).
infection (11 papers, 2007 to 2025). The state of being infected such as from the introduction of a foreign agent such as serum, vaccine, antigenic substance or organism. "hSAA-1 also induced expression of the MARCO receptor, which was downregulated during infection, similar to the SRA1, SRB1, and CD36 receptors." (PMID 37781389, 2023). "Accordingly, we found increased RNA abundance of Arg1, Socs1, Sra1, Saa1, Ciita, Marco, Mgl2, Cd209d, Cd209e, Cd209f, Ccl1, Ccl11, Ccl17, Ccl19, Ccl20, Ccl22, and Ccl24 genes in Stat2−/− mice when compared to WT mice during super-infection." (PMID 30337919, 2018). "In THP-1-macrophages, we also observed reduced expression of SRA1, ITGB5, and TIM4 receptors in response to infection with SARS-CoV-2." (PMID 35666101, 2022).
cancer (9 papers, 2015 to 2025). A tumor composed of atypical neoplastic, often pleomorphic cells that invade other tissues. "Furthermore, SRA1-deficient cancer cells exhibited increased expression of genes related to autophagy." (PMID 38584841, 2024). "Steroid receptor RNA activator 1 (SRA1) has been described as a novel transcriptional co-activator that affects cancer cell migration." (PMID 40129567, 2025). "Our analysis also demonstrated the activation of inflammatory response pathways in SRA1-deleted cancer cells." (PMID 38584841, 2024). "Among the upregulated genes, we identified a key functional signature reflecting pathways that play pivotal roles in the consequences of SRA1 gene deletion on cancer cell biology." (PMID 38584841, 2024). "Steroid receptor RNA activator 1 (SRA1), characterized as a lncRNA, which was initially characterized as a transcriptional co-activator and subsequently found to exert an impact on cancer cell migration." (PMID 38584841, 2024). "These pathways can contribute to insights into the inhibitory role of SRA1 depletion in cancer cells." (PMID 38584841, 2024). "Our study contributes to the growing body of evidence highlighting the multifaceted role of lncRNAs, particularly SRA1, in cancer metabolism and treatment response." (PMID 38584841, 2024). "Steroid receptor RNA activator 1 (SRA1) has been described as a novel transcriptional co-activator that affects the migration of cancer cells." (PMID 34011971, 2021). "The balance between protein-coding and non-coding transcripts of SRA1 is regulated by alternative splicing, and any misregulation promotes cancer development." (PMID 25978564, 2015). "This downregulation indicated a potential role of SRA1 in promoting glycolytic metabolism, and its absence might hinder cancer cells' ability to sustain rapid energy production and growth." (PMID 38584841, 2024). "This suggested that SRA1 may positively regulate the Wnt pathway, and its depletion could hinder cancer cell proliferation and self-renewal." (PMID 38584841, 2024). "Additionally, we identified the activation of cytokine-mediated signaling pathways in SRA1-depleted cancer cells." (PMID 38584841, 2024).
SRA1 also shares sentences with these, for which no sentence is quoted: infective endocarditis (4 papers); melanoma (4); Alzheimer disease (2); Insulin resistance (2); metabolic disorders (2); polycystic ovary syndrome (2); Sepsis (2); Type 2 Diabetes (2); achondroplasia (1); adenocarcinoma (1); Aortic dissection (1); Apert syndrome (1); asthma (1); autism (1); autism spectrum disorder (1); bacterial infections (1); cardiovascular disease (1); Cholestatic liver disease (1); developmental and epileptic encephalopathy, 65 (1); endocarditis (1); endometriosis (1); esophageal squamous cell carcinoma (1); gastric cancer (1); Hypertension (1); inflammation (1); Intellectual disability (1); iridocyclitis (1); ischemia (1); Jaundice (1); lentivirus infection (1).
A further 10 diseases each share a sentence with SRA1 in 1 paper.